GOLGA6L2 (golgin A6 family like 2)
Synonyms: CT105; FLJ36144
Tractability: No criterion of Open Targets' tractability assessment is met for any kind of drug.
Gene: Protein-coding gene on chromosome 15 (23,439,038 to 23,447,243, reverse strand). Ensembl gene ENSG00000174450.
Genetic constraint (gnomAD): Loss-of-function variants: 20 observed, 20.29 expected, observed/expected ratio (o/e) 0.99, 90% interval 0.69 to 1.43. The upper end of that interval is the gene's LOEUF score, 1.43, which puts it in group 5 of 6, group 1 being the genes least tolerant of losing a copy. Missense variants: 702 observed, 586.61 expected, observed/expected ratio (o/e) 1.2, 90% interval 1.12 to 1.27. Synonymous variants: 256 observed, 210.78 expected, observed/expected ratio (o/e) 1.21, 90% interval 1.1 to 1.35.
Homologues: Paralogues in human: GOLGA6L7 (36% identical), GOLGA6L22 (36% identical), GOLGA6L25 (36% identical), GOLGA6L24 (36% identical), GOLGA6L6 (36% identical), GOLGA6L1 (33% identical), GOLGA6L26 (33% identical), GOLGA6L4 (15% identical), GOLGA6L10 (15% identical), GOLGA6L9 (15% identical).
Diseases named in the same sentence as GOLGA6L2 in open-access papers:
GOLGA6L2 is named in the same sentence as 6 diseases in open-access papers, as found by Europe PMC text mining. Sharing a sentence is not in itself a finding about the gene and the disease. The quoted sentences say what the papers report.
cystic teratomas of the ovary (1 paper, 2022). "Among the prevalent mutated genes, 7 with the same variant in exons with changes in protein coding are important for the development of mature cystic teratomas of the ovary: PTGFRN, DUSP5, MPP2, PHLDA1, PRR21, GOLGA6L2, and KRTAP4-2." (PMID 36289533, 2022).
cancer (1 paper, 2015). A tumor composed of atypical neoplastic, often pleomorphic cells that invade other tissues. "Several proteins involved in cancer pathways had mutations in more than one patient, the most common being MUC4, GOLGA6L2, DSPP, FOXO6 and HLA-DRB1." (PMID 25605237, 2015).
GOLGA6L2 also shares sentences with these, for which no sentence is quoted: infection (3 papers); anaplastic astrocytoma (1); glioma (1); lung adenocarcinoma (1).